IGF2 (insulin like growth factor 2)
Diseases named in the same sentence as IGF2 in open-access papers (continued):
Sharing a sentence is not in itself a finding about the gene and the disease.
lentivirus infection (1 paper, 2025). Virus diseases caused by the Lentivirus genus. "IGF2 knockdown and control HaCaT stable transmutation cell lines (sh-IGF2 and sh-NC group) were established by lentivirus infection to investigate the effect of IGF2 synthesized and secreted by epidermal cells on dermal fibroblasts." (PMID 39744430, 2025).
lipodystrophy (1 paper, 2018). A congenital or acquired disorder characterized by abnormal loss or redistribution of the adipose tissue in the body. "On the other hand, genes specific to lipodystrophy like insulin-like growth factor II (IGF2) was shown to play a role in differentially methylated region (DMR)." (PMID 29986445, 2018).
liver tumor (1 paper, 2012). "To define the IGF signaling status in our pediatric liver tumor collection, we initially investigated the endogenous expression of the ligand IGF2 and its positive regulator PLAG1." (PMID 22401581, 2012).
lung tumour (1 paper, 2016). "Most importantly, suppression of the Ca2+ influx via blockade of nAChR or VDCC effectively suppressed the NNK-stimulated IGF2-IGF-1R axis, transformation of lung epithelial cells, and lung tumour formation in mice." (PMID 27666821, 2016). "We identified that increase in Ca2+ entry resulting from binding of NNK to nAChRs and activation of voltage-dependent Ca2+ channels (VDCCs) leads to exocytosis of IGF2 and activation of IGF-1R, ultimately promoting lung epithelial cell transformation and lung tumour formation." (PMID 27666821, 2016).
malignant rhabdoid tumor (1 paper, 2017). "In this study, we provide the first evidence that environmental stresses, including serum deprivation and chemotherapeutic agent exposure induce IGF2 upregulation in malignant rhabdoid tumor cell lines." (PMID 28521298, 2017).
migraine (1 paper, 2022). "Neuropeptides directly associated with pain or migraine from significantly differentially expressed neuropeptide prohormone genes include apelin (APLN), cortistatin (CORT), IGF2, neuromedin B (NMB), neuropeptide W (NPW), PDGFA and platelet-derived growth factor, D polypeptide (PDGFD), TAC4, and VIP." (PMID 35453627, 2022).
monoclonal gammopathy of undetermined significance (1 paper, 2016). "Here we measured total IGF1, IGF2, and intact IGFBP levels in blood and bone marrow samples from MM (n = 17), monoclonal gammopathy of undetermined significance (MGUS) (n = 37), and control individuals (n = 15), using ELISA (IGFs) and 125I-IGF1 Western Ligand Blotting (IGFBPs)." (PMID 27111220, 2016).
mucopolysaccharidosis type 7 (1 paper, 2023). Mucopolysaccharidosis type VII (MPS VII) is a very rare lysosomal storage disease belonging to the group of mucopolysaccharidoses. "The benefits of the IGF2 peptide-based glycosylation-independent lysosomal targeting (GILT) strategy for ERT were first shown in a model of mucopolysaccharidosis type VII." (PMID 37463048, 2023).
muscular dystrophies (1 paper, 2025). "While some studies have suggested that approaches to elevate muscle IGF2 peptide availability could be therapeutic for the treatment of muscular dystrophies, one indicated it would be detrimental." (PMID 40880432, 2025).
myocardial ischemia (1 paper, 2012). A disorder of cardiac function caused by insufficient blood flow to the muscle tissue of the heart. "Although 1134 potential targets of miR-376b-5p were predicted, only a few of them have been reported to be involved in myocardial ischemia, including insulin-like growth factor 2 mRNA binding protein 2, ryanodine receptor 2 and BDNF." (PMID 22396777, 2012).
myotonic dystrophy (1 paper, 2013). An inherited progressive disorder affecting the muscles. "Other regions with this function were described in the myotonic dystrophy gene DMPK, in the ICR (Imprinted Control Region) of IGF2 and in the neighboring BLU and RASSF1A loci of the 3p21.3 gene cluster region." (PMID 23874213, 2013).
ovarian endometriosis (1 paper, 2020). A non-neoplastic disorder characterized by the growth of endometrial tissue in the ovaries. "Mir-483-5p competitively binds to the 3’ UTR of mRNA Insulin-like growth factor 2 (IGF2) in ovarian endometriosis patients which results in the overgrowth of the endometrial tissue outside the uterus." (PMID 33266010, 2020).
Pain (1 paper, 2015). An unpleasant sensory and emotional experience associated with actual or potential tissue damage, or described in terms of such damage. "Results from our study indicated that immPRF treatment after nerve injury mediated inhibition of SNI-induced IGF2, and ERK1/2 activation via spinal microglia may be a possible mechanism underlying its inhibitory action on SNI-induced neuropathic pain." (PMID 26580597, 2015).
Pancreatoblastoma (1 paper, 2016). A rare malignant epithelial neoplasm arising from the pancreas. "Deregulation of IGF2 has shown to be associated with beta-cell tumorigenesis, and pancreatoblastoma is associated with chromosome 11p loss of heterozygosity and IGF2 overexpression." (PMID 27895308, 2016).
periodontal disease (1 paper, 2026). "Overall, available in vitro and in vivo evidence suggests that IGF-2 may be associated with osteogenic and immunomodulatory effects in experimental models of periodontal disease, although conclusions are limited by the small number of heterogeneous preclinical studies." (PMID 41597400, 2026).
peripheral nerve injury (1 paper, 2018). Injury to a peripheral nerve. "Major neurotrophic factors, such as IGF1, IGF2, NGF, BDNF, NT-3, and NT-4/5 can be produced by macrophages and are greatly upregulated in peripheral nerve injury, often concurrent with the influx of macrophages." (PMID 29907154, 2018).
postmenopausal osteoporosis (1 paper, 2023). Metabolic disorder associated with fractures of the femoral neck, vertebrae, and distal forearm. "miR-33a-3p affected osteogenic differentiation of hBMSCs by targeting IGF2, indicating a potential use of miR-33a-3p as plasma biomarker and therapeutic target for postmenopausal osteoporosis." (PMID 37415192, 2023).
premature ovarian failure (1 paper, 2022). "It impairs follicular development and leads to premature ovarian failure by involving mRNA expression, leading to the downregulation of the imprinted genes insulin-like growth factor 2 (Igf2) and H19, and the upregulation of Amh and Amhr2." (PMID 35328771, 2022).
prostate tumors (1 paper, 2017). "In prostate, IGF2 plays an important role as a paracrine and autocrine regulator of cell growth and was found to be expressed in prostate epithelial cells and in prostate tumor associated stromal cells." (PMID 29017567, 2017). "Thus, CNV cannot per se explain aberrant IGF2 expression in prostate tumors." (PMID 29017567, 2017). "In contrast, IGF2 LOI and CNV did not associate significantly with up- and/or down-regulation of IGF2 expression in prostate tumors." (PMID 29017567, 2017). "Interestingly, by considering all prostate tumors together without a separation in TUR-BPH, RP-BPH and RP-PCa, we found a highly significant correlation between KLF4 and IGF2 expression (p < 0.0001, Spearman’s rank correlation coefficient r = 0.668)." (PMID 29017567, 2017).
pterygium (1 paper, 2023). A wedge-shaped fibrovascular lesion arising from the bulbar conjunctiva and extending to the cornea. "RT-qPCR gene expression analysis confirmed IGF2 upregulation and demonstrated miR-483 expression in pterygium compared to normal conjunctiva (253.2-fold and 12.47-fold, respectively)." (PMID 36901760, 2023). "IGF-2 upregulation in pterygium might be explained by a possible occurrence of the IGF-2 epigenetic dysregulation, known as “loss of imprinting”, during aging." (PMID 36901760, 2023). "Since UVB exposure, responsible for irritative stimuli, induces oxidative stress-mediated NF-κB activation, it is definitely consistent with the notion that LOI-dependant IGF-2 overexpression may contribute to pterygium development." (PMID 36901760, 2023). "Therefore, we envision that IGF-2/IGF-1R co-expression in most pterygium samples would favor their interplay through the two different paracrine/autocrine IGF-2 routes for signaling transduction." (PMID 36901760, 2023). "Moreover, based on the findings that IGF-2 and miR-483 are a promising translational research area for tumor therapy, the pharmacological inhibition of mitogenic signaling by targeting these molecules could be a challenge for pterygium treatment." (PMID 36901760, 2023). "Using an immunohistochemical approach, we demonstrated an intense colocalized epithelial overexpression of IGF-2 and IGF-1R in most pterygium samples (Fisher’s exact test, p = 0.021)." (PMID 36901760, 2023). "However, the finding of 11 IGF-2+/IGF-1R- samples led us to speculate that the IGF-1R-mediated PI3K/AKT pathway would not be the unique or the main pathway activated in pterygium." (PMID 36901760, 2023).
pulmonary arterial hypertension (1 paper, 2025). Pulmonary arterial hypertension (PAH) is a group of diseases characterized by mean pulmonary artery pressure >20 mmHg and elevated pulmonary arterial resistance leading to right heart failure. "However, direct evidence linking IGF-2 to pulmonary arterial hypertension remains limited." (PMID 41169887, 2025).
rectal cancer (1 paper, 2019). A primary or metastatic malignant neoplasm that affects the rectum. "In 2012, Jo and colleagues used methylation specific PCR to examine a panel of 5 CIMP markers (i.e., CACNA1G, IGF2, NEUROG1, RUNX3, and SOCS1) in rectal cancer patients receiving 5-FU-based neoadjuvant chemoradiation." (PMID 31390840, 2019).
rectal carcinoid tumors (1 paper, 2015). "CIMP positivity was defined as the presence of four or more of the six methylated promoters [CDKN2A (p16), IGF2, MINT1, MINT2, MINT31, and MLH1], which was detected in 13% of the rectal carcinoid tumors and was associated with lymphovascular invasion." (PMID 26090613, 2015). "We selected the six markers [CDKN2A (p16), IGF2, MLH1, MINT1, MINT2, and MINT31] that were methylated in more than 5% of the rectal carcinoid tumors as CIMP markers." (PMID 26090613, 2015).
renal angiomyolipoma (1 paper, 2018). "We found that IGF2 has increased transcript expression in Tsc2-/- MEFs and TSC2— cells derived from renal angiomyolipoma of a LAM patient." (PMID 29758070, 2018).
reovirus infection (1 paper, 2004). "Reduced expression of the Ctcf gene was associated with enhanced Igf2 expression in virus-resistant cells, while forced expression of the Igf2 gene in the parental RIE-1 line was sufficient to confer resistance to lytic reovirus infection." (PMID 15333144, 2004). "L-cells expressing Igf2 were significantly more resistant to both reovirus serotypes than the parental cells, indicating that the ability of IGF-II to confer resistance to reovirus infection is not limited to a single cell or virus type." (PMID 15333144, 2004).
retinal (1 paper, 2021). "Of note, the growth-promoting effects of IGF-2 during development are mediated largely via the IR, and the retinal IR is highly sensitive to IGF-2." (PMID 33915127, 2021). "Finally, intravitreal administration of IGF-2 (mature and pro-forms) increased retinal IR and Akt kinase activity in diabetic rats." (PMID 33915127, 2021). "Thus, basal retinal IR activity may be influenced by both pro and mature forms of IGF-2." (PMID 33915127, 2021).
Rett syndrome (1 paper, 2025). A severe neurodevelopmental disorder affecting the central nervous system. "Modulation of IGF-2 activity has shown promise in correcting synaptic dysfunction and improving cognitive function in ASD animal models and in clinical trials involving related neurodevelopmental disorders such as Rett syndrome." (PMID 40526590, 2025).
serous carcinoma (1 paper, 2022). "Histopathology was remarkable for dual neoplastic processes with uterine solitary fibrous tumour (SFT) confirmed as the source of IGF2 hypersecretion on IGF-2 immunohistochemistry and a coincidental invasive high grade serous carcinoma involving the fimbria of the right fallopian tube." (PMID 36303203, 2022).
small cell lung carcinoma (1 paper, 2026). Small cell lung cancer (SCLC) is a highly aggressive malignant neoplasm, accounting for 10-15% of lung cancer cases, characterized byrapid growth, and early metastasis. "Here we identify Igf2 as the injury-activated mitogen for neuroendocrine stem cells, a facultative airway stem cell and origin of small cell lung cancer." (PMID 41676695, 2026).
Sotos syndrome (1 paper, 2022). Sotos syndrome is a rare multisystemic genetic disorder characterized by a typical facial appearance, overgrowth of the body in early life with macrocephaly, and mild to severe intellectual disability. "The DMR called for Sotos syndrome is just upstream of IGF2 and overlaps INS and INS-IGF2, with sites of moderate effect hypomethylation (Δβ > 0.2)." (PMID 36064314, 2022).
spinal muscular atrophy (1 paper, 2016). A motor neuron disease that affect the muscles, and characterized by muscle weakness and atrophy resulting from progressive degeneration and irreversible loss of the anterior horn cells in the spinal cord (i.e., lower motor neurons) and the brain stem nuclei. "IGF-2 also rescued motor neurons derived from spinal muscular atrophy (SMA) patients from degeneration." (PMID 27180807, 2016). "As we wanted to address if IGF-2 could be protective across diseases, we also treated human motor neurons derived from fibroblasts of spinal muscular atrophy (SMA) patients." (PMID 27180807, 2016).
Stillbirth (1 paper, 2022). Death of the fetus in utero after at least 22 weeks of gestation. "The sole stillbirth showed hypomethylation in the IGF2 DMR, which may have been due to the incomplete reprogramming of the cloned embryos." (PMID 35885915, 2022).
T cell lymphoma (1 paper, 2021). "These IGF2 and HGF-induced tumors showed the same anatomic distribution and histology of CD3(+)/CD20(-) T cell lymphoma." (PMID 34539876, 2021).
testicular seminoma (1 paper, 2016). A malignant germ cell tumor arising from the testis. "In their study, 9 of 10 testicular seminomas had hypomethylated IGF2/H19 ICRs (≤33% methylated)." (PMID 27034882, 2016).
transitional cell carcinoma (1 paper, 2012). A malignant neoplasm arising from the transitional epithelium, usually affecting the urinary bladder, ureter, or renal pelvis. "In this study, we found that carriers of MTHFR CC and CT mutation genotypes increased the IGF-2 gene hypomethylation frequency in their transitional cell carcinoma tissues, which was associated with the level of folate intake." (PMID 23554734, 2012). "Therefore, his study was conducted to investigate the correlation between the methylation pattern of the proto-oncogene IGF-2 in transitional cell carcinoma and the gene polymorphism of the folate metabolism enzyme, as well as their clinical characteristics." (PMID 23554734, 2012). "In our present study, the IGF-2 gene hypomethylation rate in transitional cell carcinoma was 68.3% compared with the normal healthy controls." (PMID 23554734, 2012). "According to the methylation reaction electrophoresis results, the hypomethylation frequency of the IGF-2 gene in transitional cell carcinoma tissues was about 68.3% while 12.4% was detected in normal bladder tissues." (PMID 23554734, 2012). "In summary, abnormal methylation in exon 9 of the IGF-2 gene might contribute to the initiation and development of transitional cell carcinoma." (PMID 23554734, 2012). "We compared the correlation between the IGF-2 gene methylation status and MTHFR genotype CC, CT and TT in transitional cell carcinoma tissues and normal bladder tissue." (PMID 23554734, 2012).
uterine cancer (1 paper, 2018). Primary or metastatic malignant neoplasm involving the uterine corpus and/or the cervix. "In summary, we have identified IGF2 protein expression as an independent poor prognostic biomarker in UCS, a lethal uterine cancer that disproportionately impacts black women." (PMID 29455465, 2018).
uterine carcinosarcoma (1 paper, 2018). A usually aggressive malignant neoplasm arising from the uterine corpus and less often the cervix. "The objective of this study was to investigate the relationship of insulin‐like growth factor 2 (IGF2) expression and survival in women with uterine carcinosarcoma (UCS)." (PMID 29455465, 2018).
Vestibular schwannoma (1 paper, 2025). A vestibular schwannoma (also known as acoustic neuroma, acoustic neurinoma, or acoustic neurilemoma) is a benign, usually slow-growing tumor that develops from the VIIIth cranial nerve supplying the inner ear. "Our cell communication analysis based on the curated receptor-ligand pair database showed that fibroblast in vestibular schwannoma microenvironment mainly regulated the biological behavior of tumor cells through PSAP/GPR37L1, MDK/(ITGA6 + ITGB1), IGF2/(ITGA6 + ) and MDK/LRP1 signaling axes." (PMID 40629113, 2025).
Weaver syndrome (1 paper, 2022). Weaver syndrome (WVS) is a rare, multisystem disorder characterized by tall stature, a typical facial appearance (hypertelorism, retrognathia) and variable intellectual disability. "The DMR called for Weaver syndrome overlaps the IGF2 gene and is composed of sites with a small effect size (Δβ ~ 0.05), with hypermethylation over a region of the IGF2 gene body and hypomethylation further upstream overlapping the INS and INS-IGF2 genes." (PMID 36064314, 2022). "Upstream of IGF2 overlapping INS and INS-IGF2 the pattern of hypomethylation in Sotos and Weaver syndrome was consistent." (PMID 36064314, 2022).